STAT3 (signal transducer and activator of transcription 3)
Diseases named in the same sentence as STAT3 in open-access papers (continued):
Sharing a sentence is not in itself a finding about the gene and the disease.
lung carcinoma (continued). "It has been reported that STAT3 activation could not only stimulate a series of cascades associated with the development and progression of lung cancer but also serve as a key mediator to regulate the characteristics of lung cancer stem cells (LCSCs)." (PMID 36559280, 2022). "Is α5-nAChR associated with PD-L1 via STAT3/Jab1 in lung cancer immune escape?" (PMID 35971127, 2022). "MiR-210 has been previously linked to lung cancer through the modulation of the JAK2/STAT3 pathway." (PMID 35885958, 2022). "The antitumor effects of curcumin have also been associated to inhibition of Signal Transducer And Activator Of Transcription 3 (STAT3) - which is implicated in sustaining proliferation—resulting in downregulation of cyclin B1 and consequently in G2/M phase arrest in lung cancer cells." (PMID 35685638, 2022). "Based on all the pathways given, SOD, NFKB, TGF beta, C-Myc, STAT3, Lamin-B2, Macrophage mannose receptor 1, and Histone H1.0 proteins attracted attention, which was also observed in RNA-seq, and they have also been implicated in mediating lung cancer." (PMID 35745729, 2022). "MCP1, HP and BAFF are linked to smoking in specific disease contexts and different tissues (e.g., bronchial secretions, and sgp130 has been linked indirectly to smoking via the STAT3 transcription factor pathway and modulation of tobacco carcinogen induced lung cancer." (PMID 34771561, 2021). "Hyper methylation of STAT3, on the other hand, predicted high death risk and poor survival of melanoma, metastatic melanoma, endometrial, head and neck cancer, and lung cancer patients while predicting low death risk and longer survival duration in the brain, breast, and uveal cancers." (PMID 33668805, 2021). "In lung cancer, high IL-6 activity is associated with overactivated signal transducer and activator of transcription 3 (STAT3) signalling (one mechanism of TKI resistance), which can lead to IL-6 overproduction and inflammation associated with tumour resistance and development." (PMID 34834295, 2021). "In addition, in solid cancers such as lung cancer, pancreatic cancer and intrahepatic cholangiocarcinoma, cancer-associated fibroblasts (CAFs) use STAT3 activity to secrete cytokines." (PMID 33722297, 2021). "Cancers in other organ systems (e.g. pancreas cancer, lung cancer) have shown an interdependence between KrasG12D mutation and heightened STAT3 activity, and it has also been shown that estradiol functions to increase STAT3 activation." (PMID 34735515, 2021). "Similarly, IL-6 expressed by tumor-associated macrophages (TAMs) in KRAS driven lung cancer model causes activation of STAT3 pathway with tumor progression." (PMID 33352869, 2020). "Furthermore, treatment of A549 and NCI-H292 cells with AG490, a JAK2 inhibitor, reduced FGF2 expression, proving that the JAK2/STAT3 pathway is associated with FGF2 modulation in lung cancer cells." (PMID 33121202, 2020). "For mechanism, AZ628 and BP-1-102 combination markedly abrogated MEK/ERK signaling pathway activation in KRAS-mutant lung cancer cells suggesting the combination of RAF and STAT3 inhibitors is an effective therapy for treating lung cancer cells harboring KRAS mutations." (PMID 31484165, 2019). "For example, STAT3 is frequently activated and plays oncogenic roles in non-small cell lung adenocarcinomas with the context of EGFR driver mutations, whereas low STAT3 level correlate with increased malignant progression and poor prognosis in lung cancer patients with KRAS mutations." (PMID 31296870, 2019). "Therefore, the mechanisms underlying suppression of STAT3 signaling in lung cancer cells by MVP is warranted further exploration." (PMID 31092229, 2019). "One main mechanism underlying PDLIM2 suppression of lung cancer development and therapeutic resistance involves repressing STAT3-dependent transcriptional repression of MHC-I and subsequent tumor immune evasion in the presence or absence of anti-PD-1 and chemotherapeutic drugs." (PMID 31757943, 2019).
lung carcinoma (continued). "IL-6 is the most prominent target of STAT3 and is associated with poor prognosis of lung cancer." (PMID 30634502, 2019). "Similarly, STAT-3 overexpression is associated with the metastasis of many types of cancer, including pancreatic cancer, colorectal carcinoma, gastric cancer, and lung cancer." (PMID 29794990, 2018). "Reports have suggested that elevated levels of IL-6 are mechanistically linked to poor cancer prognosis via IL-6-induced activation of miR-21 via the activation of the STAT3 pathway —miR-21 has been associated with poor survival in lung cancer in multiple studies." (PMID 28402963, 2017). "Furthermore, we drew a primary conclusion that p-STAT3 overexpression was associated with poorer overall survival of lung cancer patients (HR = 1.23; 95% CI: 1.04–1.46; P = 0.02)." (PMID 28797050, 2017). "In addition, MSI-2 stimulates migration and invasion of bladder cancers by activating the JAK2/STAT3 signaling pathway, and indirectly downregulates tight junction–associated claudins to increase lung cancer cell invasion and metastasis." (PMID 29073938, 2017). "Studies on anti-proliferation of human lung carcinoma immortalized cell line A549 were done with the use of acriflavine, cucurmin and cucurbitacin B. Use of Curcurbitacin-B caused inhibition of STAT3 pathway and induced apoptosis via oxidative stress and MAP kinase signaling pathway." (PMID 28930138, 2016). "Upregulation of the IL-6/STAT3 pathway is associated with lung cancer progression." (PMID 26517240, 2015). "Upregulation of the IL-6/STAT3 pathway is associated with lung cancer progressions." (PMID 26517240, 2015). "Indeed, a study of response to treatment with the MEK inhibitor AZD6244 using a panel of lung cancer cell lines revealed that activation of the STAT3 pathway is associated with resistance to AZD6244." (PMID 24662938, 2014). "Despite the limitations, our study provides evidence that STAT3 and myeloid infiltration associate with early metastatic disease and may be important in smoking-induced lung cancers." (PMID 23717691, 2013). "Moreover, mutations in EGFR kinase domain have been shown to mediate STAT3 activation by IL-6 production in human lung carcinomas, suggesting that EGFR-like STAT3 activation can be mediated by IL-6R or GP130 receptors in an autocrine manner." (PMID 19088723, 2009). "Similarly, MIA-690 counteracted IR-induced phosphorylation of STAT3 and NF-κB, which, in lung cancer, has been linked to the upregulation of COX-2, MMP9, and cyclin D1, factors that contribute to increased cancer cell survival, proliferation, invasion, and EMT." (PMID 40244089, 2025). "In vitro, research conducted on HCC827, HCC827ER, and H1975 lung cancer cells using a combination treatment of siRNA STAT3 with erlotinib (epidermal growth factor receptor tyrosine kinase inhibitor) revealed an association of erlotinib resistance with STAT3 activation." (PMID 38067351, 2023). "Hyperactivation of STAT3 is primarily associated with the promotion of tumor growth although it was reported that activated STAT3 might have tumor-suppressive functions in Kras-induced lung cancer in Apc-mutant mice." (PMID 34922636, 2021). "It has recently been reported that conventional therapies for lung cancer including chemotherapeutics and targeted therapies induce STAT3 activation 1,11,12, suggesting that STAT3 might be implicated in development of secondary drug resistance against conventional therapies." (PMID 32328177, 2020). "In addition, lung cancer chemosensitivity is reportedly associated with STAT3 signaling." (PMID 30931929, 2019).
lung carcinoma (continued). "It has been shown that loss of PIAS3 contributes to STAT3 activation and subsequent cell proliferation in many types of cancer, such as malignant mesothelioma, lung carcinoma, and GBM, suggesting that the PIAS3‐STAT3 pathway might also be a signaling pathway that regulates GSC stemness." (PMID 28100038, 2017). "For example, a considerable number of meta-analyses has shown the presence of a certain association between p-STAT3 overexpression and the poorer prognosis of patients with solid tumors, digestive tract tumors, gastric cancer, colorectal cancer, and lung cancer." (PMID 28797050, 2017). "In addition, xenograft experiments using the human AC cell line A549, which carries a KRAS mutation in the same amino acid as our mouse lung cancer model (G12S), showed increased tumour growth upon STAT3 knockdown, thus confirming the observations made in the mouse model." (PMID 25734337, 2015). "Moreover, it was demonstrated that WT1 loss induced senescence and decreased proliferation of lung cancer cells downstream of oncogenic KRAS signalling.STAT3 is constitutively activated in many human tumors such as prostate, lung, brain, breast and pancreatic cancer." (PMID 23936312, 2013). "S6K1 deletion reduced STAT3 phosphorylation and transcriptional activity, thereby sensitizing lung cancer to radiation." (PMID 41752050, 2026). "The results showed that GMI enhanced macrophage phagocytosis of lung cancer cells by inhibiting STAT3 and reducing CD47 expression." (PMID 41438583, 2026). "Numerous studies have highlighted that aberrant activation of STAT3 is prevalent in lung cancer and various other malignancies." (PMID 41438583, 2026). "Western blot analysis with an anti-HA antibody confirmed the sustained activation of STAT3 in these lung cancer cell lines." (PMID 41438583, 2026). "A cell assay of non-small cell lung cancer (NSCLC) revealed that apatinib triggered autophagic and apoptotic cell death via VEGFR2/STAT3/PD-L1 and ROS/Nrf2/p62 signaling in lung cancer." (PMID 41438689, 2026). "CA has been reported to suppress the STAT3 signaling pathway through ROS generation and inhibit the phosphoinositide 3‐kinase/Akt/mTOR signaling pathway in colon cancer and lung cancer." (PMID 41513589, 2026). "Lung cancer has been examined to drive neutrophils toward an N2-like phenotype through STAT3 hyperactivation to enhance cancer cell migration." (PMID 40358184, 2025). "This comprehensive review investigates the therapeutic potential of natural compounds curcumin (CUR) and resveratrol (RES) in targeting the STAT3 signaling pathway, which plays a crucial role in lung cancer progression and metastasis." (PMID 40860906, 2025). "α5-nAChR mediated immune escape via TAM and mediates CD47 expression through STAT3 signaling affecting lung cancer migration, invasion, and immune escape." (PMID 40143965, 2025). "To accurately determine the expression level of the SHH/DUSP13B/p‐STAT3 axis in osimertinib‐resistant lung cancer tissues, we collected 10 pairs of clinical lung cancer tissue specimens before and after osimertinib resistance and conducted IHC staining." (PMID 39721017, 2025). "STAT3, a key transcription factor in lung cancer, drives tumour growth and immune suppression via the mTOR and JAK pathways." (PMID 40407951, 2025). "The manuscript does not fully explore the safety profile and potential adverse effects when used as STAT3 inhibitors in lung cancer therapy." (PMID 40860906, 2025). "TNFAIP8L3 has been reported to enhance lung cancer cell proliferation, survival, and migration by activating the STAT-3 signaling pathway." (PMID 40343258, 2025). "In myeloid cells, aberrant STAT3 activation contributes to lung cancer progression by recruiting immunosuppressive cell including regulatory T cells (Tregs), MDSCs and alternatively activated macrophages (M2 macrophage) into the TME." (PMID 40407951, 2025).
lung carcinoma (continued). "Overall, these findings suggest that Melittin significantly enhances the activity of Erlotinib against lung cancer cell lines by modulating the JAK2/STAT3 signaling pathway." (PMID 40243485, 2025). "For instance, mito-Honokiol (Mito-HNK) inhibited respiratory complex I, stimulated ROS production, and suppressed mitochondrial STAT3, effectively suppressing lung cancer development and brain metastases in mouse models." (PMID 41213905, 2025). "Preclinical studies in lung cancer and melanoma models have shown that STAT3 inhibition enhances antitumor immunity by modulating the TME and reducing PD‐L1 expression." (PMID 40166646, 2025). "IL-6 is a known activator of the Janus kinase/STAT3 pathway and is involved in lung cancer metastasis." (PMID 40002883, 2025). "α5-nAChR mediates PLEK2 expression, a member of the pleckstrin protein family discovered in platelets and leukocytes, within the context of lung cancer through the regulation of STAT3." (PMID 40143965, 2025). "Meanwhile, compound K can regulate the balance between Tregs and T helper cell in lung cancer (A549 and Lewis) cells, modulate the tumor microenvironment by means of targets, such as STAT3 and PD-L1 in prostate cancer (DU 145, PC-3, and LNCaP) cells." (PMID 40490812, 2025). "It caused S-phase arrest, suppressed cell migration, and inhibited the JAK2/STAT3 (Janus kinase 2/signal transducer and activator of transcription 3) signaling pathway, suggesting its role as a lung cancer therapeutic agent." (PMID 40149610, 2025). "The inhibition of both these pathways provides an effective strategy in overcoming the activation of the STAT3, which would directly inhibit the development and progression of lung cancer." (PMID 40407951, 2025). "STK24 was recently known to promote tumorigenesis in lung cancer through STAT3/VEGFA signalling pathway." (PMID 40122572, 2025). "Several studies have shown that it is a regulator that stimulates processes via various signaling pathways, including STAT3 in lung cancer." (PMID 40143965, 2025). "STAT3 is an important target in the therapy of lung cancer as it plays various crucial roles in tumour development including tumour cell proliferation, tumour cell survival and evasion of pathogen from the immune system." (PMID 40407951, 2025). "Gene and immune system interaction analysis revealed that higher STAT3 expression correlated with a decrease in activated CD8+ T cells in lung cancer, suggesting STAT3’s role in immune suppression." (PMID 40347254, 2025). "The activation of the IL6/IL6ST/JAK/STAT3 pathway contributes significantly to lung cancer development, including tumor growth, angiogenesis, and malignant progression." (PMID 39840666, 2025). "Previous studies have reported that TNFAIP8L3 enhances lung cancer cell proliferation, survival, and migration by activating the STAT-3 signaling pathway." (PMID 40343258, 2025). "This study highlights the therapeutic potential of Melittin with Erlotinib in targeting the JAK2/STAT3/mTOR/PI3K pathways for A549 lung cancer treatment." (PMID 40243485, 2025). "Our previous study reported that inhibition of STAT3 in resistant lung cancer cells significantly increased the sensitivity of cells to gefitinib." (PMID 40703348, 2025). "Elevated gene expression of STAT3 has been observed in a broad spectrum of conditions, such as prostate cancer, lung cancer, and OSCC." (PMID 40092547, 2025). "In our lung cancer BM model, STAT3 inhibition—either alone or in combination with anti-VEGF-A monoclonal antibodies—robustly impeded BM progression." (PMID 41436606, 2025). "Compared to the control group, JAK2, STAT3, and PD-L1 protein expression was reduced in lung cancer tissues of mice from the BMSCs, QSFZYL, IFN-γ + BMSCs, and IFN-γ + BMSCs + QSFZYL groups." (PMID 40642092, 2025).
lung carcinoma (continued). "Five core targets, AKT1, EGFR, HSP90AA1, SRC, and STAT3, were identified as key mediators of its anti-lung cancer action, participating in critical signaling pathways including MAPK, PI3K-Akt, and Ras pathways." (PMID 41465428, 2025). "This suggests that NLRP3 is involved in α5-nAChR-mediated lung cancer progression and provides a new molecular mechanism for targeting the α5-nAChR/STAT3/NLRP3 axis against lung cancer." (PMID 40143965, 2025). "Cyclin Y interacts with Chk1, thereby activating the RRM2/STAT3 signaling pathway and promoting radioresistance in lung cancer." (PMID 40083692, 2025). "In conclusion, CUR and RES represent promising therapeutic agents for lung cancer management through their modulation of the STAT3 pathway." (PMID 40860906, 2025). "Under physiological conditions, STAT3 signaling is tightly regulated in healthy cells, however, in malignant cells—particularly in lung cancer—STAT3 is frequently and constitutively activated, contributing to the modulation of the tumor microenvironment." (PMID 41000397, 2025). "STAT3 is a key oncogenic factor in the JAK-STAT signaling pathway, and abnormal activation of STAT3 has been widely reported in various cancers, including lung cancer and hepatocellular carcinoma." (PMID 39852843, 2025). "Implementing these perspectives will help translate the promising preclinical findings into tangible clinical benefits for lung cancer patients and pave the way for novel, effective adjunct therapies targeting STAT3." (PMID 40860906, 2025). "Here, we tested the anti-tumor and early immunotherapeutic efficacy of TTI-101, a selective small-molecule inhibitor of canonical STAT3 signaling, in a K-rasG12D mutant lung cancer mouse model (CC-LR)." (PMID 40356899, 2025). "SAHA treatment was able to significantly up-regulate the level of STAT3 starting from 0.5 μM concentration in H460 lung cancer cells, and the maximum elevation was seen with 7.5 and 10 μM concentrations." (PMID 40941018, 2025). "The aim of this comprehensive review is to elucidate the therapeutic potential of CUR and RES as dual modulators of the STAT3 pathway in lung cancer." (PMID 40860906, 2025). "In another experimental study, apatinib inhibits the expression of PD-L1 by targeting the VEGFR2/STAT3 signaling pathway in lung cancer." (PMID 41394850, 2025). "α5-nAChR mediates the expression of PD-L1 through STAT3, and subsequently PD-L1 binds to PD-1, which mediates the activity of Tergs, CTLs, and NK cells, which influences the progression of lung cancer and participates in immune escape." (PMID 40143965, 2025). "Like other malignancies, lung cancer was predominantly impacted by wogonin's ability to regulate the NF‐κB/STAT‐3/Akt signaling pathways." (PMID 41164269, 2025). "Since STAT3 is implicated in chemo‐ and immunotherapy resistance, future studies should explore the potential of CUR and RES to sensitize resistant lung cancer cells and reverse resistance pathways." (PMID 40860906, 2025). "This manuscript is a comprehensive review that synthesizes preclinical (in vitro and in vivo) and limited clinical data regarding CUR and RES effects on the STAT3 pathway in lung cancer." (PMID 40860906, 2025). "The STAT3 pathway plays a crucial role in lung cancer by regulating cell proliferation, survival, angiogenesis, invasion, and metastasis." (PMID 40860906, 2025). "Specifically, CUR inhibits STAT3 phosphorylation and activation in lung cancer cells, leading to a 40%–60% reduction in tumor size and a significant decrease in the expression of STAT3 target genes such as cyclin D1, VEGF, MMP2, and MMP9." (PMID 40860906, 2025).